RBBP7 (RB binding protein 7, chromatin remodeling factor)
Description:
Core histone-binding subunit that may target chromatin remodeling factors, histone acetyltransferases and histone deacetylases to their histone substrates in a manner that is regulated by nucleosomal DNA. Component of several complexes which regulate chromatin metabolism. These include the type B histone acetyltransferase (HAT) complex, which is required for chromatin assembly following DNA replication; the core histone deacetylase (HDAC) complex, which promotes histone deacetylation and consequent transcriptional repression; the nucleosome remodeling and histone deacetylase complex (the NuRD complex), which promotes transcriptional repression by histone deacetylation and nucleosome remodeling; and the PRC2/EED-EZH2 complex, which promotes repression of homeotic genes during development; and the NURF (nucleosome remodeling factor) complex.
Synonyms: RBAP46; SPGFX9
Tractability: Small molecule: a structure with a bound ligand is known; it has a binding pocket of medium quality. PROTAC: UniProt records ubiquitination sites on it; ubiquitination databases record sites on it; its protein half-life has been measured; a small molecule that binds it is known.
Target class: Other nuclear protein
Gene: Protein-coding gene on chromosome X (16,839,283 to 16,870,372, reverse strand). Ensembl gene ENSG00000102054.
Subcellular location: Nucleus
Subcellular location (Human Protein Atlas): Nucleoplasm
Pathways (Reactome):
Gene expression (Transcription): ERCC6 (CSB) and EHMT2 (G9a) positively regulate rRNA expression; PRC2 methylates histones and DNA; RNA Polymerase I Transcription Initiation; Regulation of endogenous retroelements by KRAB-ZFP proteins; Regulation of endogenous retroelements by Piwi-interacting RNAs (piRNAs); Transcriptional Regulation by E2F6
Chromatin organization: HATs acetylate histones; HDACs deacetylate histones; Interaction of NuRD complexes with transcription factors; NuRD complex assembly; PKMTs methylate histone lysines; RMTs methylate histone arginines
Developmental Biology: Activation of anterior HOX genes in hindbrain development during early embryogenesis; Differentiation of naive CD4+ T cells to T helper 2 cells (Th2 cells); Transcriptional regulation of brown and beige adipocyte differentiation by EBF2
Disease: Defective pyroptosis; HCMV Early Events; Potential therapeutics for SARS
Cell Cycle: Deposition of new CENPA-containing nucleosomes at the centromere
Cell-Cell communication: Negative Regulation of CDH1 Gene Transcription
Cellular responses to stimuli: Oxidative Stress Induced Senescence
Immune System: Regulation of PD-L1(CD274) transcription
Metabolism of proteins: Neddylation
Signal Transduction: Regulation of PTEN gene transcription
Gene Ontology:
Molecular function: histone binding; protein binding; RNA binding
Biological process: cellular heat acclimation; chromatin remodeling; negative regulation of cell growth; regulation of DNA-templated transcription; brain development; heterochromatin formation; negative regulation of cell migration; negative regulation of DNA-templated transcription; negative regulation of stem cell population maintenance; negative regulation of transcription by RNA polymerase II; negative regulation of transforming growth factor beta receptor signaling pathway; positive regulation of DNA-templated transcription; positive regulation of stem cell population maintenance; regulation of cell fate specification; regulation of stem cell differentiation; response to steroid hormone
Cellular component: ATPase complex; chromosome, telomeric region; ESC/E(Z) complex; histone deacetylase complex; nucleoplasm; nucleus; NuRD complex; NURF complex; cytoplasm; histone acetyltransferase complex; Sin3-type complex
Homologues: Orthologues: rat Rbbp7 (100% identical), mouse Rbbp7 (99% identical), chimpanzee RBBP7 (99% identical), guinea pig RBBP7 (99% identical), macaque RBBP7 (99% identical), pig RBBP7 (99% identical), rabbit RBBP7 (99% identical), tropical clawed frog rbbp7 (94% identical), zebrafish rbb4l (89% identical), Drosophila melanogaster Caf1-55 (85% identical), Caenorhabditis elegans lin-53 (70% identical), Caenorhabditis elegans rba-1 (52% identical). Paralogues in human: RBBP4 (88% identical), GEMIN5 (21% identical), PEX7 (17% identical), GRWD1 (16% identical), WDR59 (16% identical), WDR73 (14% identical), ERCC8 (13% identical), WDR24 (13% identical), WDR77 (13% identical).
Diseases named in the same sentence as RBBP7 in open-access papers:
RBBP7 is named in the same sentence as 52 diseases in open-access papers, as found by Europe PMC text mining. Sharing a sentence is not in itself a finding about the gene and the disease. The quoted sentences say what the papers report.
breast carcinoma (11 papers, 2015 to 2025). "For example, RBBP7 is upregulated in many cancers, including non-small cell lung cancer, renal cell carcinoma, and breast cancer." (PMID 34086947, 2021). "Interestingly, breast cancer cell lines showing high level of RBBP7 expression were more sensitive to LSD1 inhibitor ORY-1001 (iadademstat), which effectively reduced the expression of stemness genes and CCND1." (PMID 40940894, 2025). "Another study also pointed to the association between LSD1 and stemness potential: LSD1 knockdown was shown to decrease the expression of breast cancer stem cell signature genes (SOX2, SOX9, OCT4), which was mediated by the interaction between LSD1 and RBBP7." (PMID 40940894, 2025). "Moreover, RBBP4 or RBBP7 and BPTF possess high frequency of abnormal copy number in angiosarcoma, breast cancer, pancreatic cancer, prostate cancer and gastric cancer, and are mutated in colorectal adenocarcinoma, lymphoma, melanoma, etc.." (PMID 34736517, 2021). "Additionally, in breast cancer, the transcription factor TWIST recruits an RBBP7/4-MTA2/Mi-2/HDAC1/HDAC2 complex to the proximal regions of the E-cadherin promoter for transcriptional repression via an interaction with RBBP7, which promotes breast cancer cell invasion and metastasis." (PMID 34736517, 2021).
esophageal cancer (6 papers, 2021 to 2026). A primary or metastatic malignant neoplasm involving the esophagus. "It is noteworthy that the model gene RBBP7 has been identified as a promising therapeutic target for addressing the issue of stemness in esophageal cancer." (PMID 42238592, 2026). "The stem cell markers were detected by qPCR in Eca109 cells, and the results showed that overexpression of RBBP7 upregualted the expressions of esophageal cancer stem cell markers, including SOX2, KLF4, NANOG, and OCT3/4." (PMID 35538026, 2022). "Our data indicate that hypoxia promotes the progression of esophageal cancer through an epigenetic mechanism mediated by RBBP7." (PMID 35538026, 2022). "In summary, our investigation demonstrates that the hypoxia microenvironment can induce HIF1α-dependent RBBP7-mediated up-regulation of CDK4 to promote the progression of esophageal cancer." (PMID 35538026, 2022). "We analyzed the gene expression of RBBP7 in esophagus cancer and normal tissues on the GEPIA website and found that RBBP7 is highly expressed in tumor tissues." (PMID 35538026, 2022). "The analysis showed that RBBP7 expression is significantly higher in cancer tissues than in normal tissues of esophagus cancer patients (P<0.01), and the patients with high tumor stage exhibits higher RBBP7 expression than those with low stage (P<0.01)." (PMID 35538026, 2022). "Hypoxia-induced HIF1α up-regulates RBBP7 expression, which promotes esophagus cancer cell viability, proliferation, and stemness with increased cyclin-dependent kinase 4 (CDK4) expression." (PMID 35538026, 2022). "While in another study, RBBP7 was found to promote esophageal cancer cell proliferation, consistent with our observation." (PMID 35538026, 2022). "For example, hsa_circ_0006168 regulates glycolysis in esophageal cancer cells by competitively binding miR-384 to enhance the expression of retinoblastoma-binding protein 7 (RBBP7), subsequently activating the S6K/S6 pathway." (PMID 33710802, 2021). "RBBP7 induces CDK4 expression partially mediated by HIF1α in esophageal cancer cells under hypoxia." (PMID 38028543, 2023). "In esophageal cancer, RBBP7 expression is negatively correlated with patient prognosis." (PMID 38028543, 2023). "RBBP7 can up-regulate the colony formation and the relative expression of stemness markers in esophageal cancer cells, and the role of RBBP7 in the tumor stem cells may be an exciting research field in the future." (PMID 35538026, 2022). "We hereby found that RBBP7 could promote the proliferation of esophageal cancer cells and increase stemness." (PMID 35538026, 2022). "In esophageal cancer, one study reported that RBBP7 overexpression or knockdown could significantly promote or inhibit the migration and invasion of esophageal squamous cell carcinoma (ESCC) cells without affecting apoptosis or tumor growth." (PMID 35538026, 2022). "Currently, there are relatively few reports on RBBP7 in esophageal cancer." (PMID 35538026, 2022). "Hypoxia-induced HIF1α could up-regulate RBBP7/CDK4 to promote esophageal cancer progression, which might be considered as a treatment option." (PMID 35538026, 2022). "Previous studies reported that RBBP7 was capable of promoting tumor cell proliferation, migration, invasion, and glycolysis and served as a prognosis predictor in esophageal cancer, but the roles of RBBP7 in lung cancer, especially in early-stage LUAD, are still unclear." (PMID 36503492, 2022). "In contrast, little research has been performed to decipher the role of RBBP7 in esophageal cancer." (PMID 35538026, 2022). "Further results showed that RBBP7 and CDK4 exhibit a significant positive correlation in esophageal cancer patients (r=0.3155,P<0.0001), indicating that RBBP7 might regulate the expression of CDK4." (PMID 35538026, 2022).
esophageal cancer (continued). "Eca109 and KYSE450 esophageal cancer cell lines were cultured under normoxia, hypoxia, or CoCl2-induced hypoxia conditions, which were further transfected with plasmids expressing RB binding protein 7 (RBBP7), hypoxia-inducible factor 1 (HIF1)-α, or RBBP7 shRNA." (PMID 35538026, 2022). "Next, we tested whether RBBP7 plays a role in esophageal cancer stem cells." (PMID 35538026, 2022). "We conclude that hypoxia induces high expression of RBBP7 which is at least partially mediated by HIF1α, up-regulates the expression of downstream CDK4, and thereby promotes tumor progression in esophageal cancer cells." (PMID 35538026, 2022). "A detailed analysis of RBBP7 in the OS group and DFS group on the GEPIA website indicated that RBBP7 is significantly correlated with the OS rate and DFS rate of esophagus cancer." (PMID 35538026, 2022). "We observed that the cell viability was higher in the RBBP7 overexpression group than in the vector group in both Eca109 and KYSE450 esophageal cancer cell lines." (PMID 35538026, 2022). "In order to determine the role of RBBP7 in cell function, we first overexpressed RBBP7 in Eca109 and KYSE450 esophageal cancer cell lines." (PMID 35538026, 2022). "We also found that overexpression of RBBP7 could promote the proliferation of Eca109 and KYSE450 esophageal cancer cells in colony formation experiments." (PMID 35538026, 2022). "Mechanistic analysis revealed that hypoxia-induced HIF1α could up-regulate RBBP7 to promote the expression of downstream CDK4, thereby enabling the tumor progression of esophageal cancer cells." (PMID 35538026, 2022). "RBBP7 was identified and experimentally verified to be directly targeted by HIF1α to up-regulated CDK4 in hypoxia conditions to promote viability, proliferation, and stemness of esophageal cancer cells." (PMID 35538026, 2022).
lung carcinoma (5 papers, 2015 to 2022). "In lung cancer, the region between − 428 and − 377 of the E-cadherin promoter contains a binding site for RBBP7, where RBBP7 functions as a transcriptional activator of the E-cadherin gene by binding to its promoter region, thereby repressing EMT progression." (PMID 34736517, 2021). "On the other hand, in lung cancer cells, RBBP7 acts as a transcriptional activator of the E-cadherin/CDH1 gene by binding to its promoter region thereby repressing EMT progress." (PMID 31636385, 2020).
prostate carcinoma (4 papers, 2020 to 2023). A carcinoma that arises from epithelial cells of the prostate gland. "In prostate cancer, RBBP7 interacts directly with HMGB1, which allows HMGB1 to participate in the RNA metabolic process and thus promotes cancer cell proliferation and differentiation, making the prognosis of patients with high HMGB1 expression worse." (PMID 38028543, 2023). "Our study for the first time determined the role of RBBP7 as a corepressor associated with the tumor suppressor HNF1B to repress SLUG expression and EMT phenotype in prostate cancer." (PMID 31636385, 2020). "Here, the demonstration of a critical axis of EZH2-HNF1B/RBBP7-SLUG in prostate cancer development, provides mechanistic insights of EZH2-mediated prostate tumorigenesis and molecular basis for the application of EZH2 inhibitors." (PMID 31636385, 2020). "Importantly, our study clearly demonstrates a tumor suppressive function of RBBP7 in prostate cancers when HNF1B is present." (PMID 31636385, 2020). "Here in this study, we find that the tumor suppressor HNF1B is repressed by EZH2 in prostate cancer cell lines, and functions together with RBBP7 in suppressing EMT through down-regulation of SLUG expression, which expands our knowledge of how EZH2 is involved in this deleterious disease." (PMID 31636385, 2020). "Mechanistically, HNF1B interacts with RBBP7, a component of multiple transcription repressor complexes, and represses SLUG expression and EMT process to suppress the cancer phenotypes of prostate cancer cells." (PMID 31636385, 2020). "However, RBBP7 can also bind to HNF1B as part of multiple transcriptional repressor complexes, thereby inhibiting EMT in prostate cancer via direct suppression of EMT factor SLUG expression, except that HNF1B is often repressed by EZH2 overexpression." (PMID 38028543, 2023). "However, in prostate cancer, upregulation of EZH2 suppresses the levels of the RBBP7/HNF1B transcriptional complex via direct inhibition of HNF1B expression, promoting SLUG transcription." (PMID 34736517, 2021).
Azoospermia (3 papers, 2023 to 2025). Absence of any measurable level of sperm,whereby spermatozoa cannot be observed even after centrifugation of the semen pellet. "Although mutations in the RBBP7 gene in our cohort are associated with Sertoli cell-only syndrome (SCOS) and azoospermia, previous studies have shown that mutations in different variants of this gene are linked to maturation arrest." (PMID 39932629, 2025). "In two patients, a causal variant was found that could explain their azoospermia (heterozygous variant in NR5A1 and hemizygous variant in RBBP7)." (PMID 39180390, 2025).
breast tumors (3 papers, 2019 to 2025). "While SUZ12, RBBP4 and RBBP7 were highly expressed in breast tumors, their transcription levels were either comparable to or lower in TNBC groups compared to non-TNBC groups." (PMID 41413688, 2025). "We further found that mRNAs of SAP30, HDAC1, RBBP4, and RBBP7 but not other core subunits were significantly induced in all 4 major subtypes of breast tumors." (PMID 37655663, 2023).
hepatocellular carcinoma (3 papers, 2021 to 2024). A malignant tumor that arises from hepatocytes. "For example, Kaplan–Meier curves indicated that hepatocellular carcinoma (LIHC) high expression groups for both RBBP4 and RBBP7 had significantly worse overall survival (P < 0.01) compared with low expression groups." (PMID 34086947, 2021).
prostate adenocarcinoma (2 papers, 2021 to 2024). "RBBP7 was downregulated in kidney chromophobe, kidney renal clear cell carcinoma, prostate adenocarcinoma, and STAD." (PMID 38368381, 2024).
Atrophy (1 paper, 2021). Any weakening or degeneration, especially through lack of use. "Thus, reductions in the expression of Rbbp7 may lead to increased tau acetylation, phosphorylation, and ultimately neuronal loss, thereby resulting in reductions of brain weight due to atrophy." (PMID 33978814, 2021).
brain tumors (1 paper, 2010). "For this purpose, we queried the Oncomine database and found that 4 PcG genes (EZH2, RBBP7, SUZ12, YY1) are specifically expressed in brain tumors." (PMID 20920292, 2010).
cyst (1 paper, 2023). A sac-like closed membranous structure that may be empty or contain fluid or amorphous material. "Inactivation of Caf1-55/RBBP7 in either germline cells or cyst cells in Drosophila resulted in small testes and spermatogenic failure, resembling the phenotypes of RBBP7 mutations in human patients." (PMID 37843278, 2023). "In Drosophila, knockdown of RBBP7/Caf1-55 in germ cells resulted in complete absence of germ cells and reduced testis size, whereas knockdown of RBBP7/Caf1-55 in cyst cells resulted in hyperproliferative testicular cells." (PMID 37843278, 2023).
infertile (1 paper, 2023). "Most recently, a large-scale analysis of the X chromosome in infertile men suggested that retinoblastoma-binding protein 7 (RBBP7) was the most frequently affected gene." (PMID 37843278, 2023).
invasive ductal carcinoma (1 paper, 2020). "For example, RBBP7 (RbAp46) and BIRC5 (survivin) expression in carcinoma cells is significantly higher in estrogen receptor (ER)-positive pure DCIS than in invasive ductal carcinoma (IDC)." (PMID 32156290, 2020).
Leydig cell tumor (1 paper, 2023). A sex cord-stromal tumor occurring in the testis and rarely in the ovary. "Here, we identified a deleterious hemizygous variant of X-linked retinoblastoma-binding protein 7 (RBBP7) as a potential key cause of MA, which was also found to be associated with the development of Leydig cell tumors." (PMID 37843278, 2023).
male infertility (1 paper, 2023). The inability of the male to effect fertilization of an ovum after a specified period of unprotected intercourse. "RBBP7/Caf1-55 deficiency leads to male infertility and small testis in Drosophila." (PMID 37843278, 2023). "RBBP7 rescues male infertility caused by Caf1-55 deficiency in Drosophila." (PMID 37843278, 2023). "We and others both have found that the mutations of RBBP7 gene led to spermatogenesis defects and therefore could be a pathological cause for male infertility." (PMID 37843278, 2023). "Ectopic expression of human wild-type RBBP7, rather than the mutant RBBP7, could rescue Caf1-55–linked male infertility." (PMID 37843278, 2023). "Interestingly, male infertility caused by Caf1-55 deficiency was rescued by ectopic expression of wild-type human RBBP7 but not mutant variants, suggesting the importance of RBBP7 in spermatogenesis." (PMID 37843278, 2023). "Thus, the concurrent presence of male infertility and LCT may be linked to RBBP7 mutations affecting key genome stability factors, such as histone H4 and BRCA1." (PMID 37843278, 2023).
neuroblastoma (1 paper, 2019). Neuroblastoma (NB) is the most common solid, extracranial childhood tumor. "In the case of neuroblastoma, tumors with high amplification of MYCN show hyperactivation of PRC2-associated components such as EZH2, EED, and RBBP7 with respect to non-MYCN-amplified neuroblastoma cases." (PMID 31920530, 2019).
psoriasis (1 paper, 2022). An autoimmune condition characterized by red, well-delineated plaques with silvery scales that are usually on the extensor surfaces and scalp. "However, there is no direct evidence that RBBP7 or RBBP4 is correlated with psoriasis." (PMID 35669784, 2022).